CD4 (CD4 molecule)
Diseases named in the same sentence as CD4 in open-access papers (continued):
Sharing a sentence is not in itself a finding about the gene and the disease.
tumor (continued). "Immunological studies have shown that CD4 + CD25 + Tregs can suppress the immune response of T cells to foreign and self-antigens, thereby maintaining immune tolerance and inhibiting the immune response to tumor cells, ultimately leading to immune escape of tumor cells." (PMID 40587482, 2025). "However, it is worth noting that tumor-derived mRNA allows the transfection of TAAs and co-stimulatory molecules, ensuring antigen presentation in MHC-I without requiring cross-presentation, but it cannot induce a potent CD4+ immune response." (PMID 40491907, 2025). "Interestingly, CD4+ T cells and macrophages, which are the main immune cells that kill tumor cells, were not or only slightly influenced by Spindlin-1 inhibitors." (PMID 40512144, 2025). "Cytokine and chemokine production in tumor lysates was further increased after IT treatment with VZV-vax and the HPV16 L1 peptide, suggesting that local activation of both VZV-specific CD4+ and HPV-specific CD8+ T cells could lead to broad immune activation of the local TME." (PMID 40280970, 2025). "The binding of OX40L to OX40 on the surface of activated T cells significantly enhanced the proliferation and survival of CD4+ and CD8+ T cells and the secretion of IFN-γ and IL-2, while inhibiting the immunosuppressive activity of regulatory T cells, thereby amplifying the anti-tumor immunity." (PMID 41561762, 2025). "Also, CD4+ T cells that expressed our TCR did not recognize tumor cells, indicating that our TCR is CD8-coreceptor dependent and not a super-high-affinity TCR." (PMID 39846249, 2025). "In NSCLC, heightened CD4+ T cell infiltration likely represents an innate immune response to the neoplasm, whereas an elevated proportion of PD1-positive cells may indicate immunosuppressive mechanisms within the tumor microenvironment." (PMID 39971925, 2025). "Bevacizumab, an anti-vascular endothelial growth factor (VEGF) antibody, may contribute to this association via immunomodulatory effects including normalizing tumor vasculature and enhancing the infiltration of CD4+ T-cells, CD8+ T-cells, and mature dendritic cells into the tumor microenvironment." (PMID 41149478, 2025). "In addition to inhibiting Treg function and restoring co-stimulatory signals from antigen-presenting cells, anti-CTLA-4 antibodies promote sustained activation of CD4+ and CD8+ effector T cells and mediate-Fc-dependent depletion of CTLA-4high Tregs specifically within the tumor microenvironment." (PMID 40558520, 2025). "Furthermore, an open-label phase 0 clinical trial involving six patients with metastatic BC showed promising results, with c-MET-CAR-T cell therapy leading to tumor necrosis, hemorrhage, and significant infiltration of T-cells (CD3+, CD4+, and CD8+) and macrophages (CD68+) at the injection sites." (PMID 40281554, 2025). "Furthermore, the immune cells, beyond just CD4 T cells, lead to a markedly altered tumor microenvironment of HIV-HL contrasted to HL without HIV infection." (PMID 40969752, 2025). "APOE− tumor cells may promote tumor growth by interacting with dendritic cells and CD4+ T cells via CD99‐ rather than CD6‐regulated signaling." (PMID 39810624, 2025). "Consistent with patient data, our orthotopic mouse model revealed that ADT could reshape the immune cell composition within the tumor microenvironment, increasing CD3+ T cell infiltration and a reduction in CD4+ helper T cells, indicating a shift toward CD8+ cytotoxic T cell dominance." (PMID 41262256, 2025). "These opposing effects may contribute to the absence of significant differences in the CD3+CD4+ cell phenotype (IL-17 expression) in 67NR tumor-bearing young or aged mice." (PMID 40894304, 2025). "FTY720 treatment beginning 2 days but not 8 days post tumor inoculation prevented immunotherapeutic vaccination from significantly reducing tumor burden even though any group that received FTY720 had significantly fewer CD4+ T cells within the tumor compared to animals that did not." (PMID 40196575, 2025).
tumor (continued). "Additionally, the proportions of CD4+ and CD8+ T cells in the peripheral blood of mice were also elevated, which further confirmed that M@P + L could activate the systemic anti-tumor immune response." (PMID 39743555, 2025). "Our study aimed to examine whether Treg subsets and STAT phosphorylation (pSTAT) are altered in CD4+ T-cells from the blood of CLL patients and whether these changes correlate with disease stage (Binet classification), disease duration, tumor mass size, and distribution." (PMID 40427031, 2025). "Notably, approximately 94.3% of malignant CD4 T-cells in tumor-stage lesions did not express CD5, compared to only 76.6% of malignant CD4 T cells from patch/plaque MF lesions." (PMID 41226451, 2025). "However, in the B16-OVA tumor model, we demonstrated that when the B16-OVA tumor was grafted, the immune response against the OVA CD4 epitope was also increased when mice were immunized with constructs fused with oligoDOMTM, contributing to the overall reduction in tumor growth rate." (PMID 40160825, 2025). "However, in the present study, both the YQHXJDD ELNVs and YQHXJDD groups showed weaker fluorescence intensities for CD4 and CD8 compared to the model group, which might be attributed to the more extensive omental tumor infiltration observed in the model group." (PMID 41170390, 2025). "TGFβ3/GLI2/YAP1 expression was associated with anti-tumor immune desertion, as evident by a negative association with tumor-infiltrating lymphocytes, including the CD8 T cells, CD4 T cells, B cells, Th1, gamma delta T cells (γδ T cells), and T follicular helper cells (Tfh)." (PMID 40027190, 2025). "Moreover, treatment with crizotinib or αPD-1 alone promoted greater numbers of tumor-infiltrating CD8+ T cells, IFN-γ+granzyme B+CD8+ T cells, and T effector (Teff) subsets (Th1) of CD4+ T cells in tumors than did treatment with the vehicle but substantially fewer than did the combination treatment." (PMID 38307859, 2024). "Some evidence suggests that CD4+ T cells are more amenable to lentiviral transduction than CD8+ T cells, whereas modification via CRISPR/Cas-mediated knock-in leads to equal editing of both CD4+ and CD8+ T cells, resulting in higher CD8+/CD4+ ratios, which is important for tumor control." (PMID 38255224, 2024). "In addition, CD4 + T cells may interact directly with microglia, promoting IFN-γ-dependent microglia activation and phagocytosis, necessary for tumor suppression." (PMID 38429759, 2024). "Similarly, anti‐CD4 Abs are used for targeting CD4+ T cells, whereas anti‐CD206 Abs can selectively target macrophages, especially M2 macrophages, which are involved in tumor promotion." (PMID 39434967, 2024). "While certain markers and drivers of T-cell exhaustion seen in tumor infiltrates (TILS) have been well studied in the past decade, most findings are limited to CD8+ subtypes, leaving unanswered questions if these observations carry over to their CD4+ T-cell counterparts." (PMID 39689157, 2024). "Based on the function in immune-stimulating adjuvant of ZnO, this inorganic–organic hybrid nanocomposite could reduce immune-suppressive Tregs and enhance the infiltration of CD4+ and CD8+ T cells, effectively inducing tumor antigen-specific immunity and significantly inhibiting tumor growth." (PMID 38998669, 2024). "This increase in T-helper cell (CD4+) population without an increase in total T cells was quite intriguing, indicating a shift in phenotype without an increase in overall production or requirement of T cells to the tumor microenvironment." (PMID 39204325, 2024). "Importantly, while tumor mice had a higher CD4/CD8 ratio compared with non-tumor mice, suggesting a specific reduction of CD8 cells due to the presence of tumor, this was not the effect of DIO, which caused a general reduction in both CD4 and CD8 BM T cells." (PMID 38351079, 2024). "However, some evidence suggests that tumor-infiltrating CD4+ and CD8+ T cells do not correlate with OS or DFS." (PMID 39372398, 2024).
tumor (continued). "Moreover, the proportions of immune cells in the peripheral blood and CD4+ T cells and DCs in the tumor tissues were not significantly different." (PMID 38291470, 2024). "Indeed, at four weeks post-tumor injection, mice depleted of CD4+ or CD8+ cells developed tumors, unlike MOC2-CIITA-injected mice, where 25% of the animals remained tumor-free." (PMID 39035008, 2024). "However, the GPX4 inhibitor, which acts as an antioxidant, displays greater sensitivity towards CD8+T cells and CD4+T cells, leading to a preferential induction of ferroptosis in killer T cells rather than tumor cells." (PMID 38853203, 2024). "E3K CAR-T cell composition (CD4+/CD8+ ratio), activity in vitro against endosialin+ and endosialin– cells, and expansion and activity in vivo in syngeneic tumor models as well as in tumor-naive healthy and wounded mice and tumor-bearing endosialin knockout mice was assessed." (PMID 38413223, 2024). "Similarly, we found the infiltrate levels of CD4+ T cell, neutrophil, macrophage and dendritic cells were highest in IC2 among all clusters, which presents the typical phenotypes of immune “hot” tumor for IC2." (PMID 38971948, 2024). "Interestingly, the protective effect of immune CD4+ and CD8+ T cells was comparable to the effect obtained with total immune spleen cells, further reiterating the importance of both T cell subpopulations in the anti-tumor response." (PMID 39035008, 2024). "This suggests that ccRCC tumors overexpressing the NEK2 gene may be a hot tumor for 1 day because our findings indicated a strong link between NEK2 expression and the majority of markers of activated T cells in ccRCC, specifically CD8+/CD4 + T cells." (PMID 38758909, 2024). "In addition, immunohistochemical staining for ITGAL and multiplex immunofluorescence (mIF) staining for ITGAL, CD20, CD68, CD4, and CD8 from tissue microarrays containing 118 tumor tissues and paired paracancerous tissues from patients with NSCLC were performed." (PMID 38646528, 2024). "The survival analysis suggested that a higher number of tumor cells around CD4+Tregs (IM, 51.33 vs. no reached, P = 0.020; TC, 39.93 vs. not reached, P < 0.001) and CD8+Tregs (IM, 46.93 vs. not reached, P = 0.002; TC, 45.03 vs. not reached, P < 0.001) showed a lower RFS both in IM and TC." (PMID 39093404, 2024). "For example, different ZipFv can be used to regulate the function of CD4+ T cells (to help secrete cytokines) and CD8+ T cells (to kill cancer cells directly), thus improving the release of some anti‐tumor cytokines, which help CAR‐T cells to achieve better anti‐tumor outcomes." (PMID 38456710, 2024). "Flow cytometry gating on the malignant CD4+ PD-1high T cells showed their low dependence on glucose, and they were significantly more dependent on OXPHOS as compared to the CD4+ PD-1low cells in the AITL tumor, WT CD4+, CD8+, and CD19+ cells and tumor-infiltrating CD19+ and CD8+ cells." (PMID 38897995, 2024). "Indeed, RocA was found to significantly promote the degranulation and intracellular production of IFN-γ in CD4+ TILs but did not activate CD8+ TILs in LLC tumor tissues." (PMID 38833034, 2024). "Interestingly, whereas depletion CD4+ T cells did not impact the anti-tumor efficacy, CD8+ T cells depletion dramatically abolished MSA-2 caused tumor inhibition, accelerated tumor growth and increased tumor mass." (PMID 38592428, 2024). "Furthermore, we conducted an analysis of immunosuppressive cell populations, with a specific focus on Treg cells (CD4+Foxp3+ stained) and exhausted PD1+CD8+ T cells (PD1+CD8+ stained), utilizing multiplex immunofluorescence staining within the tumor microenvironments." (PMID 38163894, 2024). "However, in a model of triple-negative breast cancer (TNBC), despite close proximity to effector T cells, dormant tumor cells are not eliminated and support a CD4+ and FoxP3+ Treg-rich microenvironment." (PMID 38561826, 2024).
tumor (continued). "In summary, we observed elevated levels of THEMIS+ CD4+ T cells in tumor tissues from non-responsive patients, suggesting that this cell population may modulate the efficacy of anti-PD-1 treatment by regulating CD4+ T cell development." (PMID 38948071, 2024). "A recent study has shown that tumor progression and anti‐tumoral T‐cell response are sex‐dependent in a syngeneic B16‐F10/BL6 mouse model; however, in contrast to our observation, such study showed that females had less tumor growth rate and higher CD4+ and CD8+ T‐cell infiltrates compared to males." (PMID 38327091, 2024). "These structures could be visible by staining, including panel I: CD8+ T cells, CD4+ T cells, PD-1+ cells, PD-L1+ cells, Foxp3+ regulatory T cells; and panel II: CD19+ B cells, CD56+ NK cells, CD68+ macrophages, CD163+ M2 macrophages, cytokeratin+ tumor cells." (PMID 38637495, 2024). "Notably, bivariant, dual marker density plots also showed that a discrete collection of CEACAM1+PD1+ cells could be detected in all manually gated subsets of CD4+ T cells within the treatment-resistant PBMC and tumor samples." (PMID 38956268, 2024). "In addition, the proportions of CD4+T cells showed no significant changes in the tumor tissue in the Ftsj1 KD group compared with the control group." (PMID 38339348, 2024). "Furthermore, the discovery of tumor-specific CD4+ T cells, which recognize MHC II-restricted tumor antigens such as tyrosinase, CDC27, gp100, MAGE-3, Melan-A/MART-1, Eph receptor, and NY-ESO-1, underscores their importance in tumor immunity." (PMID 38887597, 2024). "Furthermore, CD4+ T cells fulfill a regulatory role in immune responses, while CD8+ T cells serve as vital effector cells in the context of anti-tumor responses, and an elevated CD8+ ratio is indicative of a more potent anti-tumor effect." (PMID 38898927, 2024). "extensively depicted the dynamic cell heterogeneity among tumor epithelial cells, immune cells, myeloid cells, endothelial cells, and stromal cells of infiltrative BCC and revealed the inflammatory characteristics and CD4+ Treg-derived impaired immunity of BCC by scRNA-seq." (PMID 39558960, 2024). "The density of CD4+ T cells (r = − 0.5187, p = 0.0001), CD8+ T cells (r = − 0.3221, p = 0.0225), CD68+ macrophages (r = − 0.4097, p = 0.0031), and PD-L1+ cells (r = − 0.4119, p = 0.003), and the number of TLSs (r = − 0.4665, p = 0.0006), were negatively correlated with tumor size." (PMID 38254190, 2024). "Furthermore, Spearman correlation analysis validated a negative correlation between the tumor volume and the number of infiltrated Cd4+ and Cd8+ T cells in KO tumor tissue, whereas the number of infiltrated αSma+ cells increased with tumor volume." (PMID 38942797, 2024). "Moreover, IHC staining of HCC tumor tissues from our cohort also revealed significant correlations of B4GALNT1 levels with the numbers of infiltrating CD163 + TAMs (R2 = 0.06, p = 0.019) and CD4 + T cells (R2 = 0.05, p = 0.038)." (PMID 39616302, 2024). "Likewise, the prevalence of Fusobacterium nucleatum in human tumor tissues of OSCC was inversely correlated with the infiltration of B cells, CD4+ T helper cells and type 2 macrophages (M2), sculpting a less immunosuppressive TME and favoring the disease prognosis." (PMID 39120310, 2024). "Immune profiling of shGsdmc tumors revealed comprehensive remodeling of the tumor microenvironment, characterized by decreased immunosuppressive cells like MDSCs and M2 TAMs, alongside increased anti‐tumor immune cells, such as M1 TAMs, cytotoxic CD8+ cells, and T‐helper CD4+ cells." (PMID 39297408, 2024). "Further, MCT11 was not expressed by other tumor-infiltrating immune cells, as tumor-infiltrating CD4+ T cells, B cells, natural killer cells, dendritic cells, polymorphonuclear-myleoid derived suppressor cells (PMN-MDSCs), monocytic-myeloid derived suppressor cells (M-MDSCs) and neutrophils." (PMID 39516648, 2024).
tumor (continued). "Immunophenotype by multi‐color flow cytometry for the tumor and spleen showed that other than CD8+ T‐cell changes, there was no significant changes for CD4+ T cell, tumor DC (dendritic cell), tumor macrophage, tumor immature myeloid cells, and tumor neutrophils." (PMID 38686626, 2024). "This suggests that the lack of concordance may be due to the low infiltration of CD4+ T cells in the tumor." (PMID 39136024, 2024). "Notably, positive correlations were found with dendritic cells, CD4+ T cells, and neutrophils, suggesting that TGFBR2 may play a significant role in enhancing the immune regulatory network within the LUAD tumor microenvironment." (PMID 39364312, 2024). "To determine whether enhanced anti-tumor immunity in Opnfl/flFoxp3YFP-Cre mice is Treg intrinsic, we transferred purified CD3+CD4+ and CD3+CD8+ effector T cells (T regulatory cells were depleted as we sorted Foxp3-YFP-) into Rag2−/− hosts along with Opn-deficient Tregs or wild-type controls." (PMID 39272810, 2024). "Thus, to test for relationships between K17 expression the tumor inflammatory microenvironment, we analyzed intratumoral and peritumoral CD8+ T cells, CD4+ T cells, CD16+/CD163− tumor-targeting (M1) macrophages and CD16+/CD163+ tumor promoting (M2) immune cells ratios across all cases." (PMID 38730319, 2024). "Mouse models combining CD4+ and CD8+ T cells for adoptive transfer can induce bystander killing of antigen-negative tumor cells, which may prevent acquired tumor resistance caused by downregulation or deletion of the targeted tumor antigens." (PMID 38412034, 2024). "Notably, TREM2+ Macrophages promoted the transition of CD4+ T cells into an anti-tumor phenotype through inhibitory receptors such as PDL2 and other inhibitory receptors, while CD4_Tcm further enhanced the differentiation of TREM2+ Macrophages into a tumor-promoting phenotype via the TGF-β pathway." (PMID 38948071, 2024). "Interestingly, CQ treatment did not alter the level of IFN-γ+ TNF-α+ CD4+ T cells and PD-1+ T cells infiltrated into the tumor." (PMID 39247196, 2024). "The percentages of tumour-infiltrating immune cells, including CD4+ T cells, CD8+ T cells, and NK cells, are significantly reduced in DNAM-1−/− mice, suggesting that DNAM-1 plays an essential role as activating receptor for immunosurveillance in the tumour microenvironment." (PMID 38893071, 2024). "Immune cells in tumor-draining lymph nodes and tumor-infiltrating lymphocytes from mice treated with IR and anti-CTLA4 demonstrated an upregulation of genes in T-cell functions and enrichment in both CD4+ and CD8+ T-cell populations compared to mice given IR and the isotype control." (PMID 39199612, 2024). "However, the inhibitory effect of TIGIT was observed specifically on the CD8+ T‐cell‐mediated antitumour responses in tumour‐bearing mice, rather than NK cells, CD4+ T cells, or Tregs." (PMID 38279870, 2024). "Furthermore, MSCs from tumours demonstrated lower CD39 and CD73 protein expression compared to non-cancerous tissue, and this expression correlated with decreased ATP metabolism and the suppression of CD4+ T-cell proliferation." (PMID 39120301, 2024). "Tumor cells undergoing ICD can be used as vaccines or as immune adjuvants to attract and promote DCs maturation, which in turn acts as powerful antigen-presenting cells (APCs) to activate adaptive immune responses, particularly CD8 killer T cells and CD4 helper T cells." (PMID 39014462, 2024). "Furthermore, our investigation revealed that PGRN expression on CD8+TILs was significantly higher than that on infiltrating CD4+TILs and macrophage cells in the TME of WT tumor-loaded mice, further confirming the significant impact of PGRN on CD8+ TILs in the TME." (PMID 38744851, 2024).